GDNF (glial cell derived neurotrophic factor)
Diseases named in the same sentence as GDNF in open-access papers (continued):
Sharing a sentence is not in itself a finding about the gene and the disease.
Parkinson disease (continued). "In view of the potency of GDNF in promoting the survival of dopaminergic neurons, these novel findings have implications for the utilization of melatonin in neuroprotective strategies, especially in Parkinson's disease." (PMID 15511288, 2004). "Additionally, in the CNS, pretreatment of dopaminergic neuronal progenitors in a Parkinson's disease model with perlecan‐conjugated laminin E8 fragments resulted in enhanced maturation and neurite extension of progenitor cells through activation of BDNF–TrkB and GDNF–RET signaling." (PMID 41555564, 2026). "We propose that serum GDNF levels may serve as a potential biological marker for the early prediction of brain white matter changes in PD-MCI patients, providing a convenient, non-invasive, and cost-effective tool for the early screening of Parkinson’s disease." (PMID 39513043, 2024). "Notably, we found that increased GDNF levels have a protective effect in supranigrally delivered lactacystin model of Parkinson’s disease; this effect is not mediated by protecting DA cell bodies in the substantia nigra pars compacta, but by enhancing the dopaminergic function in the striatum." (PMID 26681446, 2015). "Although GDNF and NRTN are two highly potent NTFs in the treatment of Parkinson’s disease (PD), the outcomes of clinical trials are not very successful." (PMID 29966219, 2018). "Given the recent systematic and meta-analysis which concluded that glial-derived neurotrophic factor (GDNF) and neurturin do not improve motor symptoms in people with Parkinson's it is timely to consider alternative factors that may hold potential." (PMID 29698669, 2018). "Our key results show that baculovirus-produced non-mammalian GDNF and GFRα1 stimulate human RET phosphorylation as well as signal through the MAPK/ERK cascade to promote the survival of dopaminergic neurons affected by Parkinson’s disease." (PMID 28467503, 2017). "Although NG2+ microglia have been reported to express a neuroprotective factor, GDNF, it appears that in the present scenario this neuroprotective factor did not contribute to neuronal survival in the 6-OHDA-induced Parkinsonism model." (PMID 22398979, 2011). "Glial cell line-derived neurotrophic factor (GDNF) is a potent neurotrophic protein for dopaminergic and other neurones and shows robust neurorestorative and neuroprotective effects in nonhuman primate models of Parkinson’s disease when administered to targets within the CNS." (PMID 30808022, 2019).
depression (85 papers, 2011 to 2026). "Several studies have reported associations between GDNF levels and various mental disorders, including mood disorders, anxiety, depression, and bipolar disorder." (PMID 39881227, 2025). "GDNF levels were shown to be significantly decreased in depression involved in the dopamine system and has been linked to a potential treatment in drug abuse." (PMID 38362105, 2024). "Given this, depression was a risk factor for PD patients with sleep disorders (OR > 1, p < 0.05), and GDNF and ADO were protective factors in preventing sleep disorders (OR < 1, p < 0.05)." (PMID 36831743, 2023). "Altered levels of GDNF were observed in association with depression and the analysis of the blood of mood disorder patients has shown a reduction of GDNF and ARTN during the depressive state." (PMID 32252363, 2020). "Further research is needed that includes pre-menopausal women to compare the effects of NW and NW with RSA training on BDNF and GDNF levels, as well as on cognitive function, risk of depression, and cardiopulmonary efficiency." (PMID 33192480, 2020). "It is well known that high levels of endogenous neurotrophins, BDNF and GDNF, in the brain and peripheral blood reduce the hippocampus gray matter loss, improve memory, and reduce the occurrence of depression in the elderly (see section “Introduction”)." (PMID 33192480, 2020). "The etiology of depression in PD is complex, and the exact mechanism underlying the effect of GDNF on depression is elusive." (PMID 29615705, 2018). "To clarify this issue, here we present an association analysis between eight SNPs of the GDNF gene and mood characteristics assessed by the Hospital Anxiety and Depression Scale (HADS) questionnaire using data from 708 healthy Caucasians." (PMID 24324616, 2013). "One GDNF SNP (rs1981844) showed association with the HADS depression scale, with higher scores in the presence of the minor allele [F(1,1133) = 5.086, p = 0.02431, η2 = 0.004, power = 0.615]." (PMID 24324616, 2013). "Given our results showing lower serum GDNF levels in the PWECD group, we hypothesize that GDNF deficiency-induced neurotransmitter disruption may be a key mechanism in the pathogenesis of depression comorbid with epilepsy." (PMID 39474368, 2024). "Recently, GDNF has been the focus of multiple genetic association analyses in our laboratory, revealing associations of certain SNPs in the gene with neuropsychiatric conditions including anxiety, depression, smoking, addiction, and gambling." (PMID 38674063, 2024). "In addition, several studies showed that GDNF is known to the mechanism underlying depressive disorders." (PMID 38362105, 2024). "In addition, GDNF has been reported to associate with a variety of neural diseases, such as Hirschsprung disease, depressive disorder, and Tourette syndrome." (PMID 33336053, 2020). "Finally, we investigated the mRNA expression of the neurotrophic factors nerve growth factor (NGF) and glial cell line-derived neurotrophic factor (GDNF) that have both been discussed to be implicated in chronic stress/depression as well as in nociception." (PMID 30142161, 2018). "Here we explored the association of 8 GDNF polymorphisms with anxiety and depression." (PMID 24324616, 2013). "Since mood disorders are often accompanied by drug abuse, and impaired dopaminergic signaling is a well-known factor in the pathogenesis of depression, we raised the question whether GDNF gene variants might be risk factors of depression or anxiety." (PMID 24324616, 2013). "Thus, we speculate that the depression phenotype in aged ART-conceived mice offspring might be associated with the reduced GDNF and functions of dopaminergic neurons." (PMID 34605773, 2021). "Reduced levels of both GDNF and BDNF were linked to cognitive decline, with BDNF also decreased in PD patients with depression." (PMID 41697575, 2026).
depression (continued). "Preclinical data show that animals exposed to chronic unpredictable stress exhibit depression-like behavior and decreased GDNF expression in the hippocampus, that is reverted by chronic tricyclic antidepressant treatment." (PMID 40642294, 2025). "The onset of depression has been associated with structural changes in the hippocampus and a decrease in BDNF, GDNF, and NGF." (PMID 40260589, 2025). "It has been reported that GDNF levels were lower in mood disorder patients in comparison to the control group, and decreased as the degree of depression increased significantly." (PMID 38918365, 2024). "GDNF expression in the striatum improves dopaminergic transmission and is related to psychiatric conditions, such as depression, anxiety, stress, schizophrenia, and addictive behaviors." (PMID 38928583, 2024). "In fact, according to some studies, there are lower serum GDNF levels in patients suffering from depression, with a subsequent increase after pharmacological treatment." (PMID 39170712, 2024). "The decrease in GDNF expression in the hippocampus of rats that showed signs of depression due to exposure to stress was treated with exogenous GDNF." (PMID 39770989, 2024). "In a post-mortem study, an increase in GDNF was observed in the parietal cortex (site of emotion regulation) of patients with depressive disorder, while in other studies, a reduction in the expression of its mRNA was measured." (PMID 39170712, 2024). "Growing evidence showed that peripheral glial cell line-derived neurotrophic factor (GDNF) was reduced in depression." (PMID 35562946, 2022). "MiR-511 was found to negatively regulate GDNF family receptor alpha 1 in the basolateral amygdala in the depression, which changed the quality of GDNF signalling and then affected the downstream MAPK pathway." (PMID 35562946, 2022). "Clinical studies have reported lower serum GDNF in patients with major depressive disorder and increases in serum GDNF by antidepressant treatment." (PMID 34765515, 2021). "GDNF expression has been found to be decreased in patients with major depression, and antidepressant treatment can significantly increase GDNF levels in patients with major depression." (PMID 34385905, 2021). "The present study is novel to the literature to demonstrate the role of disease marker of peripheral and CNS levels of GDNF in depression and MDD and its role with antidepressant treatment." (PMID 34078872, 2021). "On the other hand, the expression of GDNF gene at both protein and mRNA levels is higher in patients with depressive disorders than in the control group." (PMID 33804468, 2021). "The levels of nerve growth factor (NGF) and glial cell line derived neurotrophic factor (GDNF) are decreased in depression and the magnitude of dysregulation of these factors correlates with depressive symptoms severity." (PMID 33255237, 2020). "Reduced GDNF mRNA and serum levels have been detected in patients with major depression and serum GDNF level was negatively correlated with the severity of depressive symptoms." (PMID 33013310, 2020). "Whereas in some cases serum GDNF increased considerably in cases of depression while in other investigations it decreased remarkably in patients with MDD." (PMID 31853432, 2019). "Accumulating recent studies showed that GDNF has the ability to improve brain function and that it plays an important role in various neuropsychiatric disorders such as depression, Alzheimer’s disease (AD), and aging." (PMID 31905925, 2019). "BMI: Body mass index; F/M: Female/male; GDNF: Glial cell line-derived neurotrophic factor; Ham-D: 17-item Hamilton depression rating scale; N: Number; SEM: Standard error mean." (PMID 31853432, 2019). "Very little work has been done to establish a relationship between GDNF and major depression and among the few findings; most of the results obtained were conflicting." (PMID 31853432, 2019).
depression (continued). "A meta-analysis study showed a decrease in the expression of GDNF in the brain of patients with depression." (PMID 30728786, 2018). "Studies have shown that the reduction of GDNF and BDNF levels in the brain of patients with depression is associated with decreased hippocampal nerve regeneration." (PMID 30728786, 2018). "A recent study has demonstrated that the GDNF is important for the pathogenesis of depression, such as the decrease of the GDNF protein and mRNA expression in the serum and hippocampus of depressive individuals." (PMID 30728784, 2018). "Together, these findings suggest the protein and mRNA expression levels of GDNF decreased in patients with depression." (PMID 28819313, 2017). "Meanwhile, multiple studies have reported significantly increased GDNF in serum and parietal cortex of bipolar depression as well as late-onset depression patients compared with normal controls." (PMID 28819313, 2017). "We have shown that the protein and mRNA expression levels of GDNF decreased in patients with depression." (PMID 28819313, 2017). "Multiple studies have previously investigated the relation between GDNF and the development and treatment of stroke and depression." (PMID 28819313, 2017). "To date, the scope of GDNF applications has been greatly expanded and includes the treatment of Huntington’s disease, amyotrophic lateral sclerosis, chronic pain, depression and addiction, as well as the regeneration of the sciatic nerve." (PMID 24926342, 2014). "While there is strong evidence linking BDNF to stress and depression, other neuronal growth factors are also involved, most notably glial cell-line derived neurotrophic factor (GDNF) and nerve growth factor (NGF; Hayley and Litteljohn, 2013)." (PMID 24723864, 2014). "The upregulation of NGF, BDNF, GDNF, and other neurotrophic factors is considered for treatment of depression and neurodegenerative diseases." (PMID 23878590, 2013). "Both elevated and reduced GDNF plasma concentrations have been reported in patients with late-onset depression, major depression or bipolar disorder." (PMID 24324616, 2013). "Notably, alterations in GDNF levels have been observed in patients with major depressive disorder and bipolar disorder, suggesting a potential role for GDNF in the pathophysiology of these conditions." (PMID 39881227, 2025). "Clinical studies have further shown that GDNF levels are negatively correlated with Hamilton Depression Rating Scale (HAMD) scores, suggesting that GDNF may serve as a diagnostic marker for PSD." (PMID 40529498, 2025). "They noted a more severe manifestation of depression in patients with a lower GDNF level." (PMID 40141452, 2025). "Dysregulation of NTFs, particularly brain-derived neurotrophic factor (BDNF), ciliary neurotrophic factor (CNTF), glial cell line-derived neurotrophic factor (GDNF), and nerve growth factor (NGF), has been implicated in various cerebral disorders, including epilepsy and depression." (PMID 39474368, 2024). "Further studies could have important clinical implications using BDNF and GDNF as targets for specific pharmacological therapies for depression." (PMID 39170712, 2024). "Recent studies have found that reduced levels of GDNF in plasma, serum, and lacrimal fluid are significant for diagnosing and predicting depressive disorders, providing further support for our hypothesis." (PMID 39474368, 2024). "Lower levels of GDNF may be involved in the pathophysiological processes of depression, and GDNF levels increase after antidepressant treatment." (PMID 38020612, 2023). "Antidepressants could increase GDNF mRNA and protein levels, suggesting the increased GDNF might contribute to the improvement of depression." (PMID 37089920, 2023). "Lacrimal GDNF levels were assessed in patients with bipolar disorder and major depressive disease (MDD), and it was shown that a low GDNF concentration in LF could be a potential biomarker of depression." (PMID 38069144, 2023).
depression (continued). "KIT prevented CORT-induced depression-like behavior, spatial memory impairment, and decreases in hippocampal cell survival, the number of hippocampal new-born immature neurons, accumbal dendritic spine density and GDNF mRNA." (PMID 34765515, 2021). "However the increased permeability of BBB in depression is high enough to let the GDNF passing through BBB." (PMID 34078872, 2021). "In a meta-analysis conducted by Lin and Tseng assessing the concentration of glial neurotrophic factor (GDNF) in patients with depression, it was confirmed that in this group of patients the blood levels of GDNF are significantly reduced compared to healthy subjects." (PMID 33804468, 2021). "Vitamin D3 also strengthens the nerve growth factor (NGF) and glial derived neurotrophic factor (GDNF), and GDNF may have a role in depression." (PMID 34473420, 2021). "The protein and mRNA expression of GDNF decreased in patients with depression." (PMID 34531719, 2021). "However, there is a study on the effects of pharmacological treatment on GDNF levels in women with schizophrenia and depression." (PMID 33192480, 2020). "Despite the exact connection of GDNF in the etiology of depression is not fully understood, still, its neuroprotective capacity might make it a highly interesting future target for antidepressant treatment." (PMID 31853432, 2019). "Although GDNF is a member of the transforming growth factor β family that is widely expressed in the brain, however, there is very little data that states a link between changes in this neurotrophic factor and major depression." (PMID 31853432, 2019). "As this is only a preliminary study, to understand the exact relation between serum GDNF levels with MDD and to establish these findings as predictors for the assessment of depression risk, further studies with a large and more homogeneous population are required." (PMID 31853432, 2019). "The expression of the GDNF mRNA in the VTA was significantly correlated with anhedonia, despair, and locomotor activity, suggesting that the GDNF is associated with maternal deprivation-induced depression-like behaviors." (PMID 30728784, 2018). "In addition, the Spearman analysis demonstrated that the GDNF protein level negatively correlated with the value of Hamilton depression rating scale (HAMD) in PSD patients (correlation coefficient = −0.328, P = 0.047)." (PMID 28819313, 2017). "The severity of depression in PSD positively correlated with the degrading of GDNF." (PMID 28819313, 2017). "The precise mechanisms contributing to the decreased GDNF protein and mRNA levels in depression remain unknown." (PMID 28819313, 2017). "Previous studies have indicated that the level of glial cell line-derived neurotrophic factor (GDNF) may be correlated with stroke and depression." (PMID 28819313, 2017). "Animal models continue to examine the relationship between epigenetic controls and cognitive and mental health issues such as anxiety and depression, including the potential role of Glial Cell Line-Derived Neurotrophic Factor (GDNF) in the development and maintenance of individual coping strategies." (PMID 26095868, 2015). "The pathophysiology of major depressive disorders could also involve GDNF, which plays a role in the development and function of hippocampal cells." (PMID 24723864, 2014). "One possible reason for the lack of significant effects of GDNF polymorphisms on depression in the present study is that depression scores were quite low in our non-clinical sample." (PMID 24324616, 2013). "Although BDNF has undoubtedly received the most attention, emerging and recent evidence indicates that other growth factors, most notably glial cell-line derived neurotrophic factor (GDNF) (a member of the transforming growth factor beta family) is also likely involved in depression." (PMID 24312008, 2013).